KRAS (KRas proto-oncogene, GTPase)
Diseases named in the same sentence as KRAS in open-access papers (continued):
Sharing a sentence is not in itself a finding about the gene and the disease.
colorectal cancer (continued). "Compared with BRAF‐mutated tumors, KRAS c.34G>T mutants showed more frequent LINE‐1 hypomethylation, a biomarker for early‐onset colorectal carcinoma." (PMID 39039804, 2024). "The pharmacological rationale of the combination of FTD/TPI and bevacizumab was confirmed in preclinical models, and in particular on mice bearing SW48 (KRAS wild type) and HCT116 (KRAS mutated) human colorectal carcinoma xenografts." (PMID 39911824, 2024). "Kirsten Rat Sarcoma (KRAS) is the most commonly mutated oncogene in colorectal carcinoma (CRC)." (PMID 39125664, 2024). "And also to investigate the expression of KRAS-downstream proteins (p-ERK, p-AKT, and P65) in colorectal carcinoma harbor mutant and wild-type KRAS." (PMID 38465160, 2024). "The objective of this study was therefore to determine the frequency of KRAS and BRAF mutations in colorectal carcinomas in our institution." (PMID 39364024, 2024). "While this has been explored more comprehensively in KRAS-mutant pancreatic cancer, there has been some success with colorectal cancer." (PMID 37190303, 2023). "A recent study showed that inhibiting MAP4K2 with BAY61-3606 can sensitize KRAS wild-type colorectal cancer cells to AZ628, a RAF kinase inhibitor, suggesting a potential therapeutic strategy for treating colorectal cancer." (PMID 38111008, 2023). "When applied to TCGA datasets, specific subpopulations such as the invasive subtype in colorectal cancer and copy number high pancreatic adenocarcinoma were predicted to have higher KRAS dependency." (PMID 37141389, 2023). "Of the three main isoforms that are found to be mutated in cancer—KRAS, HRAS, and NRAS—KRAS is the most commonly mutated isoform, present in up to 90% of pancreatic cancer (PDAC), 50% of colorectal cancer, and 30% of lung cancer (LUAD)." (PMID 37581538, 2023). "BCAM is highly expressed in KRAS-mutant hepatic metastases from colorectal cancer, and inhibition of BCAM/LAMA5 interferes with the adhesion of colorectal cells to vascular endothelial cells, thereby reducing metastatic growth." (PMID 36672394, 2023). "Anti-KRAS antibodies can be used in combination with anti-EGFR antibody (Cetuximab) in KRAS wildtype advanced colorectal cancer (CRC) patients to concurrently kill tumor cells that has developed resistance to anti-EGFR therapy due to acquired KRAS mutation." (PMID 37051535, 2023). "A similar KRAS electromobility shift, indicative of covalent compound binding, was observed following AZ’1569 treatment across the colorectal cancer panel, suggesting that differential sensitivity was unlikely due to differences in target engagement." (PMID 36279564, 2023). "In the whole cohort, 20 patients (13%) had TMB-high status (using the classical cut-off of 10 mutations per Mb), 8 (5.2%) had MSI, and 18 patients (12%) presented a KRAS mutation—especially in NSCLC and colorectal cancers." (PMID 37108755, 2023). "A unique finding of our study is that the mode of Fn infection differs between colorectal cancers with the SSP phenotype and those with KRAS mutations." (PMID 37772997, 2023). "In the KRAS G12D LS513 colorectal cancer model, SJ-C1044 was administered orally at 20, 40, or 80 mg/kg, once a day (QD), and significant tumor growth suppression was observed in a dose-dependent manner." (PMID 37504287, 2023).
colorectal cancer (continued). "One of the main findings presented here is that incidence of Fn infection is significantly high in colorectal cancer exhibiting not only SSP phenotype including MSI-H, MLH1 hypermethylation or BRAF mutations but also KRAS mutations." (PMID 37772997, 2023). "This study explored the use of radiomic features from multi-parametric MRI scans to predict the KRAS mutation status, tumor staging, MRF invasion, and EMVI in colorectal cancer patients." (PMID 38066782, 2023). "This noncovalent compound targets both the inactive and active form of KRAS G12D, the most common KRAS mutation in PDAC and colorectal cancer." (PMID 37581538, 2023). "Only a small fraction of EGFR positive advanced colorectal cancers expressing wild type KRAS respond to anti-EGFR mAbs, and acquired resistance also commonly occurs." (PMID 37170144, 2023). "GNAQ and KRAS were identified as driver genes in both colorectal adenoma and colorectal cancer samples." (PMID 37546388, 2023). "In KRAS mutant colorectal cancer, combinations of CDK4/6 and MEK inhibitors have been found to be synergistic in reducing in vitro cell growth, and to be effective in patient-derived xenograft models." (PMID 37126527, 2023). "In colorectal cancer, oncogenic KRAS drives the production of lactic acid, leading to its accumulation in the TME whereby it promotes activation-induced cell death of tumor-specific CD8+ T cells." (PMID 37581538, 2023). "The mutant KRAS colorectal cancer cell lines were demonstrated to upregulate the genes involved in ribosome biogenesis." (PMID 37373047, 2023). "Mismatch repair deficiency (d-MMR)/microsatellite instability (MSI), KRAS, and BRAF mutational status are crucial for treating advanced colorectal cancer patients." (PMID 38201408, 2023). "In this systematic review, we evaluated the role of AI in predicting MSI status, KRAS, and BRAF mutations in colorectal cancer." (PMID 38201408, 2023). "KRAS mutations can abnormally activate the MAPK signaling pathway, causing the continuous activation of downstream ERK1/2 and promoting colorectal cancer malignant progression." (PMID 37370699, 2023). "Pre-disposition for KRAS and BRAF genetic mutations has been suggested as a possible explanation for the previous findings of increased relative risks of colorectal cancer after BOTs." (PMID 37807065, 2023). "Deletion of the KRAS gene is most dramatic for the survival of pancreatic cancer cells (Supertarget) as well as for lung and colorectal cancers." (PMID 37297004, 2023). "This has been settled with multiple recent studies concluding that patients with a KRAS-mutant colorectal cancer (25–52%) do in fact have significantly worse prognosis compared to those with wildtype KRAS." (PMID 37190303, 2023). "For example, miR-16 has been shown to inhibit the proliferation, migration, and promote apoptosis of colorectal cancer cells by downregulating KRAS." (PMID 37465677, 2023). "All colorectal cancer tumors harbored alterations in the WNT pathway regulator APC; 6 (60%) were KRAS mutated, which were mutually exclusive from BRAF V600E mutations [n = 2 (20%)]." (PMID 36426653, 2023). "Combination MEK and CDK4/6 inhibition has been shown to be synergistically reduce KRAS-mutant colorectal cancer growth both in vitro and in vivo." (PMID 37190303, 2023).
colorectal cancer (continued). "Many common alterations associated with advanced colorectal cancer were detected, including loss of function events in APC (OMIM 611731), and hotspot KRAS (OMIM 190070) and BRAF (OMIM 164757) variations (V600E, D595G, and G469A)." (PMID 38051531, 2023). "MET amplification has been detected after anti‐EGFR antibody treatment of KRAS‐wild‐type colorectal cancer." (PMID 36416133, 2023). "While KRAS-mutant selective therapy has come a long way, more work is required to make this an effective and viable option for patients with colorectal cancer." (PMID 37190303, 2023). "In order to survive glucose deprivation, the KRAS mutant colorectal cancer cells, were found to upregulate the expression of GLUT1 and during this glucose deprivation, the wild type cells were found to acquire new mutations in the KRAS gene." (PMID 37110218, 2023). "Kirsten rat sarcoma (KRAS) gene is one of the most common mutated oncogenes in numerous cancer types, such as non-small cell lung cancer (NSCLC), colorectal cancer (CRC), and pancreatic ductal adenocarcinoma (PDAC)." (PMID 36675641, 2023). "The functional cooperation between AP-1 and the Hippo pathway was further highlighted by a study in which the TEAD coactivator YAP1 was identified among the genes able to rescue the effect of KRAS suppression in KRAS-transformed colorectal cancer cells." (PMID 37176013, 2023). "Studies demonstratedthat patients with colorectal cancer who undergo a transformation from mutant to wild-type KRAS have a more favorable survival prognosis." (PMID 37520536, 2023). "Alterations in KRAS have been found in 25% of all human cancers, with pancreatic cancer (90%), colorectal cancer (45%), and lung cancer (35%) being the types of cancer with the highest mutation rates." (PMID 37376135, 2023). "Our results raise the question of why and how Fn infection is enriched in colorectal cancer with SSP phenotypes including MSI-H, MLH1 hypermethylation, and BRAF mutations, and, independently, KRAS mutations." (PMID 37772997, 2023). "Fn infection should be considered as a candidate risk factor specific to colorectal cancers with the SSP phenotype and with KRAS mutations." (PMID 37772997, 2023). "Negative results for the EGFR-driven cell lineHCC827 and the KRAS-driven patient-derived colorectal cancer xenograftPDX-pY-IP are presented for comparison." (PMID 37053475, 2023). "KRAS and BRAF mutation rates in colorectal cancer (CRC) reported from various mono-ethnic studies vary amongst different ethnic groups." (PMID 38139338, 2023). "Previous studies showed that the mutations of KRAS and BRAF had positive correlations to lung metastasis of colorectal cancer and papillary thyroid carcinoma, respectively." (PMID 36161776, 2023). "In colorectal cancer, the concordance rate of KRAS status decreases when the time to metastasis increases." (PMID 38003476, 2023). "Development of colorectal cancer (CRC) involves activation of Kirsten rat sarcoma viral oncogene homolog (KRAS) signaling." (PMID 37716979, 2023). "KRAS mutation is a significant driving factor of tumor, and KRASG12V mutation has the highest incidence in solid tumors such as pancreatic cancer and colorectal cancer." (PMID 37287989, 2023). "How does the prognostic profile of KRAS sequence variation compare between patients with young-onset and late-onset colorectal cancer?" (PMID 38032636, 2023).
colorectal cancer (continued). "Trials are being conducted for TNO155 with a ribociclib combination in KRAS-WT non–small cell lung cancer and KRAS-mut colorectal cancer (ClinicalTrials.gov NCT04000529)." (PMID 36752207, 2023). "For example, in the analysis of KRAS, NRAS, and BRAF mutations in 850 colorectal cancer (CRC) cases, the concordance rate was 88.6%, accounting for all mutations including those not in the Idylla cartridge by design." (PMID 37174112, 2023). "KRAS in particular is mutated in lung and pancreatic ductal adenocarcinoma (PDAC) as well as colorectal cancer." (PMID 36443441, 2023). "The rat sarcoma virus (RAS) oncogene is frequently mutated in colorectal cancer with its most frequent isoform, Kirsten RAS (KRAS), influencing the mitogen-activated protein kinase (MAPK) pathway." (PMID 37190303, 2023). "Hsa-miR-100 is up-regulated in kirsten rat sarcoma viral oncogene homolog (KRAS) mutant colorectal cancer exosomes and confers hsa-miR-100 mediated cell communication." (PMID 36961325, 2023). "Based on this study, it has shown activities for various BRAF V600E or KRAS mutant cancers, including melanoma and colorectal cancer in vitro and in vivo." (PMID 36872366, 2023). "We also analysed the CCLE protein expression data of KRAS wild-type versus mutant cell lines across cancers and from lung or colorectal cancer." (PMID 37198494, 2023). "Our results demonstrated that circIFNGR2 induces cetuximab resistance in colorectal cancer cells by indirectly regulating target gene KRAS by sponging miR-30b at the post-transcriptional level." (PMID 36639711, 2023). "In a KRAS-mutant colorectal cancer context, there is a completed Phase1b/2 trial awaiting reports that examined the safety and efficacy of Telaglenastat in combination with Palbociclib." (PMID 37190303, 2023). "When applied to lung adenocarcinoma, pancreatic adenocarcinoma, and colorectal cancer patient datasets, the K20 model identified specific subpopulations that correlate with greater dependency on KRAS." (PMID 37141389, 2023). "BRAF and KRAS are two key oncogenes that determine response to anti-EGFR therapies in colorectal cancer patients." (PMID 37483495, 2023). "We found that KR12 selectively bound mutant KRAS and led to observable anti‐tumor effects in colorectal cancer models, most likely due to the induction of cell death as a consequence of mutant KRAS silencing." (PMID 36262061, 2023). "In KRAS mutant colorectal cancer lines with combined EGFR and MEK inhibitor resistance, compensatory PI3K/AKT signaling plays an important escape mechanism." (PMID 37154160, 2023). "In CIMP-low colorectal cancer, KRAS upregulates zinc-finger DNA-binding protein, ZNF304, which binds promoters and recruits a corepressor complex with DNMT1, leading to DNA hypermethylation." (PMID 37234978, 2023). "MRI radiomics was assessed to predict the KRAS status and tumor staging in colorectal cancer patients across different imaging platforms to improve the personalized treatment decisions and outcomes." (PMID 38066782, 2023). "EGFR expression has been used as a biomarker to treat colorectal cancer (CRC) patients with wild-type KRAS in the US (patients with metastatic CRC and HNSCC in the EU)." (PMID 37519889, 2023). "KRAS mutated-CRC and L/E colorectal cancer had the fourth highest Fn loads, and MSS-CRC had the lowest Fn loads." (PMID 37772997, 2023). "We conclude that circIFNGR2 induces cetuximab resistance in colorectal cancer cells by indirectly regulating target gene KRAS by sponging miR-30b at the post-transcriptional level." (PMID 36639711, 2023).
colorectal cancer (continued). "The frequency of KRAS mutations in patients with highly aggressive cancers such as pancreatic ductal adenocarcinoma (PDAC), colorectal cancer, and non–small cell lung carcinoma (NSCLC) is very high representing 90%, 35%, and 30% of all cases, respectively." (PMID 38051103, 2023). "RAS mutations are the most frequent proto-oncogene mutations, in which KRAS mutation has the highest incidence in solid tumors (about 86% of the three RAS mutations), i.e., approximately 90% in pancreatic cancer and 40% in colorectal cancer." (PMID 37287989, 2023). "In this study, we demonstrated that KRAS-mutant colorectal cancers were less sensitive to L-OHP and more sensitive to statins, and statins improved L-OHP hyposensitivity and cytotoxic effect in KRAS-mutated colorectal cancer cells." (PMID 37069612, 2023). "Because somatic mutations in KRAS are linked to poor response to anti-epidermal growth factor receptor (EGFR) focused therapy, KRAS is a predictive biomarker for colorectal cancer." (PMID 36950511, 2023). "The ability of KRAS inhibition to stimulate antitumor immunity is also supported by conditional genetic mouse models of KRAS-mutant colorectal cancer or PDAC in which suppression of KRAS expression increased influx of T cells." (PMID 37581538, 2023). "In colorectal cancer KRAS (including Raf/Ras/MEK/Erk), EGFR, c-Met, Apo2L, FAK, NF-κB are plausible molecule targets." (PMID 36966394, 2023). "The co-clinical study at MDACC utilizes PET imaging and radiotracers of glutamine metabolism to assess the response of individualized cancer therapeutics for wild-type (WT) KRAS colorectal cancer (CRC) patients." (PMID 36961012, 2023). "The last guidelines for managing colorectal cancer emphasize the importance of biomarkers (MSI status, KRAS, and BRAF mutations) in advanced stages (stage II-III-IV)." (PMID 38201408, 2023). "Targeting CXCR2 has been shown to synergize with ICB in multiple preclinical models of KRAS-mutant colorectal cancer and PDAC, providing a potential combination therapy for the treatment of KRAS-mutant patients with cancer in the clinic." (PMID 37581538, 2023). "Assessment of KRAS status is mandatory in patients with late-stage colorectal cancer (CRC) before initiating targeted therapy." (PMID 37849806, 2023). "KRAS, the most frequently mutated RAS isoform (85%), is found predominantly in pancreatic, lung and colorectal cancer." (PMID 37020037, 2023). "CC-90003, a covalent ERK1/2 inhibitor, disrupts signaling pathways and impacts cell growth and survival, particularly in KRAS-mutant cells, indicating its therapeutic potential in colorectal cancer." (PMID 37842645, 2023). "Only 18% of colorectal cancer patients in the last decade with Kirsten rat sarcoma viral oncogene homolog (KRAS) wild-type tumors received anti-epidermal growth factor receptor (EGFR) antibodies." (PMID 37308981, 2023). "We therefore used INCERTS to identify KRAS-reactive TCRs from individuals with pancreatic or colorectal cancer who were immunized with a mutant KRAS peptide vaccine (ClinicalTrials.gov: NCT04117087)." (PMID 37776855, 2023).